SLC6A15 (solute carrier family 6 member 15)
Description:
Functions as a sodium-dependent neutral amino acid transporter. Exhibits preference for the branched-chain amino acids, particularly leucine, valine and isoleucine and methionine. Can also transport low-affinity substrates such as alanine, phenylalanine, glutamine and pipecolic acid. Mediates the saturable, pH-sensitive and electrogenic cotransport of proline and sodium ions with a stoichiometry of 1:1. May have a role as transporter for neurotransmitter precursors into neurons. In contrast to other members of the neurotransmitter transporter family, does not appear to be chloride-dependent.
Synonyms: NTT73; SBAT1; hv7-3; FLJ10316; V7-3
Tractability: Small molecule: it belongs to a druggable protein family. Antibody: its Gene Ontology location is reachable by antibodies, with high confidence; UniProt predicts a signal peptide or a membrane-spanning region. PROTAC: ubiquitination databases record sites on it; its protein half-life has been measured; a small molecule that binds it is known.
Target class: SLC superfamily of solute carriers; SLC06 neurotransmitter transporter family; Electrochemical transporter; Transporter
Gene: Protein-coding gene on chromosome 12 (84,859,491 to 84,913,629, reverse strand). Ensembl gene ENSG00000072041.
Subcellular location: Membrane
Subcellular location (Human Protein Atlas): Nucleoli; Vesicles
Pathways (Reactome):
Transport of small molecules: Amino acid transport across the plasma membrane; SLC-mediated transport of neurotransmitters
Gene Ontology:
Molecular function: alanine:sodium symporter activity; branched-chain amino acid:sodium symporter activity; L-asparagine:sodium symporter activity; neutral L-amino acid:sodium symporter activity; proline:sodium symporter activity; protein binding; amino acid transmembrane transporter activity; neurotransmitter transmembrane transporter activity; transmembrane transporter activity
Biological process: neutral amino acid transport; amino acid transport; L-leucine transport; neurotransmitter transport; proline transport; sodium ion transmembrane transport; alanine transport; amino acid transmembrane transport; asparagine transport; carboxylic acid transmembrane transport
Cellular component: membrane; plasma membrane
Genetic constraint (gnomAD): Loss-of-function variants: 23 observed, 54.63 expected, observed/expected ratio (o/e) 0.42, 90% interval 0.3 to 0.6. The upper end of that interval is the gene's LOEUF score, 0.6, which puts it in group 2 of 6, group 1 being the genes least tolerant of losing a copy. Missense variants: 629 observed, 764.06 expected, observed/expected ratio (o/e) 0.82, 90% interval 0.77 to 0.88. Synonymous variants: 293 observed, 267.63 expected, observed/expected ratio (o/e) 1.09, 90% interval 0.99 to 1.21.
Homologues: Orthologues: chimpanzee SLC6A15 (99% identical), macaque SLC6A15 (96% identical), rabbit SLC6A15 (94% identical), pig SLC6A15 (93% identical), guinea pig SLC6A15 (92% identical), dog SLC6A15 (92% identical), mouse Slc6a15 (92% identical), rat Slc6a15 (91% identical), tropical clawed frog slc6a15 (83% identical), zebrafish slc6a15 (76% identical). Paralogues in human: SLC6A17 (66% identical), SLC6A19 (37% identical), SLC6A20 (35% identical), SLC6A18 (35% identical), SLC6A16 (32% identical), SLC6A5 (30% identical), SLC6A8 (30% identical), SLC6A14 (29% identical), SLC6A7 (29% identical), SLC6A13 (28% identical), SLC6A9 (28% identical), SLC6A3 (28% identical), and 6 more.
Diseases named in the same sentence as SLC6A15 in open-access papers:
SLC6A15 is named in the same sentence as 21 diseases in open-access papers, as found by Europe PMC text mining. Sharing a sentence is not in itself a finding about the gene and the disease. The quoted sentences say what the papers report.
depression (24 papers, 2013 to 2025). "While loss of SLC6A15 function was reported to be associated with depression, increased KLHL36 expression has been tentatively correlated with suicide attempts." (PMID 40355756, 2025). "In patients with major depressive disorder, the SLC6A15 rs1545843 A allele has also been associated with white matter integrity in the parahippocampal cingulum, a brain region involved in emotional regulation." (PMID 37374342, 2023). "CHRM2 has been associated with nicotine dependence, while SLC6A15 has been associated with depression disorders." (PMID 37298272, 2023). "The results of these studies indicate that the SLC6A15 gene affects the predisposition to depression through alterations in glutamate neurotransmission in the hippocampus, HPA axis activity, and stress susceptibility." (PMID 27723767, 2016). "The authors identified a single nucleotide polymorphism (SNP), rs1545843 about 690 kb downstream of SLC6A15 on chr12q21.31, that was associated with unipolar depression at genome-wide significance (p = 1.41e-09) in a meta-analysis across seven samples." (PMID 23874702, 2013). "The SLC6A15 rs1545843 AA genotype has been associated with depression in PD patients." (PMID 37374342, 2023). "SLC6A15 encodes neuronal amino acid transport and was previously reported as a depression gene." (PMID 36291662, 2022). "It has been showed, that the decreased Slc6a15 expression, due to genetic or environmental factors, might alter neuronal circuits related to the susceptibility for major depression." (PMID 33673282, 2021). "It is possible that the Slc6a15 gene is associated with the major depressive disorder." (PMID 33673282, 2021). "Notably, both mice and human studies emphasized the importance of SLC6A15/v7-3 in the development of depression, of which the mechanism is associated with a neuronal circuits alteration that raises susceptibility to depression." (PMID 32372980, 2020). "As hippocampal expression of SLC6A15 has been linked to depression in humans, the differences in feeding behavior of the SLC6A15 mice might have been a manifestation of their resistance to depression-induced anhedonia caused by isolation stress." (PMID 24023709, 2013). "The SLC6A15 gene encodes a member of the solute carrier family 6 protein family, which plays an essential role in amino acid transport in neurons and might be associated with major depression." (PMID 35906672, 2022). "Interestingly, SLC6A4 and SLC6A15 gene variants have been associated with age at depression onset." (PMID 36557240, 2022). "Slc6a15 recognizes neutral amino acids such as proline, which can be further used in the biosynthesis of glutamate, a neurotransmitter implicated in depression pathophysiology and treatment, and has recently emerged as a susceptibility gene for major depression." (PMID 29882086, 2018). "The changes in Adora1, Slc6a15, and Comt expression may result in changes in the function of encoded proteins and subsequent alterations within adenosine, glutamatergic, and monoaminergic systems, all of which are critically involved in depression pathophysiology and treatment." (PMID 29882086, 2018). "Convergent data from human studies, animal models and pharmacological investigations suggest a possible role of SLC6A15 in major depressive disorder." (PMID 23874702, 2013). "Many of the amino acid transporters in the SLC6 family are known to play important roles in several pathological conditions including obesity (SLC6A14) and major depression (SLC6A15)." (PMID 23672601, 2013). "Interestingly, SLC6A15 was grouped with SLC6A19 and SLC6A20 (that are interacting with ACE2) in a recent review of SLCs, and it has been linked to the hippocampus and depression." (PMID 40667466, 2025). "In addition, the family comprises potential pharmaceutical targets, such as B0AT2 (SLC6A15), ATB0,+ (SLC6A14) and SIT1 (SLC6A20), which are genetically associated with depression, cancer and severity of Covid-19 infection, respectively." (PMID 39159813, 2024).
depression (continued). "In addition, we compare models of NTT4 and B0AT2 (SLC6A15), a close homolog with overlapping substrate and profile expression, whose inhibition is suggested to alleviate anxiety and depression." (PMID 39310277, 2024). "In humans, the SLC6A15 gene was previously involved in depression." (PMID 30913280, 2019). "The SLC6A15 gene has been identified as a novel candidate gene for major depressive disorder (MDD)." (PMID 27723767, 2016). "Here it was found, in a whole genome association study, that allelic variants of SLC6A15 increased the risk of acquiring major depression, although the mechanism behind this is not known." (PMID 23672601, 2013). "Finally, the mRNA level of genes (i.e. Adora1, Comt, and Slc6a15) in the murine prefrontal cortex, which may play a role in the pathophysiology and/or pharmacotherapy of depressive disorder was examined." (PMID 39048810, 2024). "In our study we have evaluated the expression of the selected genes, which may play a role in the pathophysiology and treatment of depression or the mechanism of DPCPX and istradefylline action (i.e., Adora1, Slc6a15, Comt)." (PMID 33673282, 2021).
Anxiety (5 papers, 2016 to 2024). Intense feelings of nervousness, tension, or panic often arise in response to interpersonal stresses. "Recent data presented that Slc6a15 knockout rodents exhibit reduced depressive and anxiety behavior, whereas the overexpression of Slc6a15 in the hippocampus resulted in mood disorders." (PMID 39048810, 2024). "Previous research provided supportive roles for SLC6A15 in modulating anxiety and depressive-like behavior." (PMID 35326239, 2022). "Consistent with human data, SLC6A15 knockout mice exhibited less anxiety- and depressive-like behavior in response to chronic social stress compared to wild-type mice, while SLC6A15 overexpression mice possessed increased anxiety-like behavior." (PMID 30239845, 2019). "In a very recent animal study, a SLC6A15-knockout mouse showed anxiety- and depressive-like behaviors under chronic social stress compared to its wildtype littermate, and the expression of the glutamate receptor (GluR1) has been shown to be regulated by SLC6A15 expression." (PMID 27723767, 2016).
Insulin resistance (3 papers, 2013 to 2023). Increased resistance towards insulin, that is, diminished effectiveness of insulin in reducing blood glucose levels. "We identify SNPs in the human SLC6A15 that are associated with body mass index and insulin resistance in males." (PMID 24023709, 2013). "Another miRNA that could play a role in insulin resistance is miRNA-let-7b-5p, which has been shown to interact directly with SLC6A15: a gene associated with the insulin resistance of metabolic disorders." (PMID 37373351, 2023). "miRNA-let-7b-5p inhibits SLC6A15 expression via its effects on the SLC6A15 3′-untranslated region (3′-UTR) and is thought to promote insulin resistance in C2C12 myotube cells." (PMID 37373351, 2023).
asthma (2 papers, 2015 to 2022). "A multi-stage GWAS study in children with childhood AD and asthma found new genetic loci (rs9357733 positioned in EFHC1 on chromosome 6p12.3 and rs993226 between TMTC2 and SLC6A15 on chromosome 12q21.3) that were specific for AD-asthma march phenotype." (PMID 35455494, 2022).
Obesity (2 papers, 2013 to 2015). Accumulation of substantial excess body fat. "We also report testing associations between SLC6A15 genomic markers with obesity-related phenotypes in two independent human samples." (PMID 24023709, 2013). "We identified an association of markers in SLC6A15 with obesity related phenotypes in each of two independent samples of boys." (PMID 24023709, 2013). "As leucine has been reported to suppress diet-induced obesity in mice, we examined its effects on high fat diet-induced obesity in SLC6A15 KO mice." (PMID 24023709, 2013). "SLC6A15 is thus well positioned to regulate cellular compartmentalization of leucine and other BCAA in ways that could contribute to the influences of these nutrients on food intake, body weight and other obesity-related phenotypes." (PMID 24023709, 2013).
ovarian carcinoma (2 papers, 2021 to 2022). A malignant neoplasm originating from the surface ovarian epithelium. "Meanwhile, the SLC6A15 mRNA expression was significantly reduced in ovarian cancer cell lines with a chemotherapy-resistant phenotype." (PMID 34796198, 2021). "Particularly, siRNA-mediated knockdown of seven genes, CASC10, ATP11B, EMP1, GAS1, SLC6A15, GALNT13, and PDLIM3, significantly reduced cell proliferation of ovarian cancer cells." (PMID 35887085, 2022).
allergic disease (1 paper, 2015). An immune response that occurs following re-exposure to an innocuous antigen, and that requires the presence of existing antibodies against that antigen. "We identified seven genome-wide significant loci, of which two susceptibility loci, in EFHC1 on chromosome 6p12.3 and between TMTC2 and SLC6A15 on chromosome 12q21.3 were associated with allergic disease for the first time." (PMID 26542096, 2015).
gestational diabetes (1 paper, 2022). Carbohydrate intolerance first diagnosed during pregnancy. "Unfortunately, there are scarce publications on linking HMGA2, CRTC2 and SLC6A15 genes to gestational diabetes, so further research on this topic needs to be carried out to enable the comparison of our findings presented in this study with other data." (PMID 35454338, 2022).
glioma (1 paper, 2025). A benign or malignant brain and spinal cord tumor that arises from glial cells (astrocytes, oligodendrocytes, ependymal cells). "For instance, in U87-MG glioma and A549 cells, alanine uptake is facilitated by SNAT1, SNAT2, SNAT5, SLC6A15 (B0AT2), SLC7A6 (y+LAT2), SLC1A4 (ASCT1), and SLC1A5 (ASCT2), and many of these transporters are also involved in glutamine transport." (PMID 40716744, 2025).
melanoma (1 paper, 2016). A malignant, usually aggressive tumor composed of atypical, neoplastic melanocytes. "An exception is represented by melanoma cells, in which SLC6A15 is highly up-regulated." (PMID 27685888, 2016).
cancer (6 papers, 2016 to 2024). A tumor composed of atypical neoplastic, often pleomorphic cells that invade other tissues. "The transporter SLC6A15, also down-regulated in both cancer cell lines, is involved in the transport of 11 amino acids." (PMID 37299011, 2023). "In many cancer cells, amino acid transporters are upregulated to enable rapid cell growth and are therefore potential drug targets e.g. as SLC1A5, SLC6A15, SLC7A5, and SLC7A11." (PMID 29868606, 2018). "Remarkably, expression of the ortholog human gene—SLC6A15—is mostly down-regulated in the NCI-60 cells panel, the US National Cancer Institute (NCI) panel of 60 human cancer cell lines grown in culture." (PMID 27685888, 2016). "Two other sodium-independent large amino acid transporters, SLC43A1 and SLC43A2 are also absent, leaving SLC6A15 encoding a known transporter of BCAA found in the mammalian brain, and SLC7A6, an antiporter exporting Arg and Lys in exchange for Leu, Ile and Gln also expressed in brain and cancers." (PMID 37918802, 2023).
tumor (2 papers, 2022). "SLC6A15 was found to be down-regulated in all stage 1–3 samples, and other studies have identified this gene as a tumor suppressor." (PMID 35659616, 2022).
heart disease (1 paper, 2023). "Although one (Gatb) has already been linked to heart disease in the literature, the other three phenotypes (Cnot6l, Slc6a15, Sytl4) describe novel findings worth further exploration." (PMID 37221250, 2023).
psychiatric disorder (1 paper, 2013). A disorder characterized by behavioral and/or psychological abnormalities, often accompanied by physical symptoms. "Our data suggest that genetic variants in the SLC6A15 locus change the activity of the amino acid transporter and might thus influence its neuronal function and the risk for stress-related psychiatric disorders." (PMID 23874702, 2013). "Given this convergent evidence for a possible role of SLC6A15 in MDD, we aimed to further explore potential functional variants that could impact the amino acid transport of this protein and by extension neuronal function and possibly the risk for stress-related psychiatric disorders." (PMID 23874702, 2013).
SLC6A15 also shares sentences with these, for which no sentence is quoted: atopic march (1 paper); eczema (1); Infertility (1); metabolic syndrome (1); mood disorder (1); nicotine dependence (1); Tay-Sachs disease (1).